Y_RNA (Y RNA )
Gene: Miscellaneous RNA gene on chromosome 2 (120,651,273 to 120,651,374, forward strand). Ensembl gene ENSG00000201006.
Homologues: Orthologues: chimpanzee Y_RNA (98% identical), macaque Y_RNA (92% identical), guinea pig Y_RNA (78% identical). Paralogues in human: Y_RNA (82% identical), Y_RNA (81% identical), RNY3 (80% identical), Y_RNA (80% identical), RNY3P1 (79% identical), Y_RNA (79% identical), Y_RNA (78% identical), Y_RNA (77% identical), RNY3P14 (76% identical), Y_RNA (76% identical), RNY3P11 (75% identical), RNY3P16 (75% identical), and 90 more.